IL1B (interleukin 1 beta)
Diseases named in the same sentence as IL1B in open-access papers (continued):
Sharing a sentence is not in itself a finding about the gene and the disease.
tularemia (8 papers, 2011 to 2020). Tularemia is an infection caused by the bacterium Francisella tularensis. "Although production of the pro-inflammatory cytokines IL-1β, IL-6 and TNFα is delayed during tularemia, mice deficient for these cytokines or the relevant receptors are more susceptible to Ft infection." (PMID 27926940, 2016). "Of note, inflammasome-mediated resistance to Francisella tularensis is mediated by both IL-1β and IL-18, and mice deficient in either cytokine are resistant to tularemia, while those deficient in both IL-1β and IL-18 are sensitive." (PMID 22241984, 2011). "IL-1β deficient mice have a lower probability to survive tularemia." (PMID 22783145, 2012). "Later in pulmonary tularemia, the release of inflammatory cytokines (IL-1β, IL-6, TNFα, etc.)and DAMPs/alarmins (e.g. HMGB1, S100A9) are suggested ‘drivers’ of host death." (PMID 27015566, 2016). "Our results also suggest that the diminished levels of IL-1β and IL-18 in the lungs of Nlrp3-/- mice may be sufficient to support their critical protective function during pulmonary tularemia." (PMID 27926940, 2016). "Collectively, these studies indicated that IL-1β and IL-18 may contribute to protection from tularemia but it remains unclear to what extent, through which mechanism, and under which conditions." (PMID 25768794, 2015). "Serum levels of eotaxin, G-CSF, IFNα, IFNγ, IL-1β, IL-2, IL-6, IL-8, IL-10, IP-10, MCP-1, MIP-1α, MIP-1β, and PDGF were significantly increased in tularemia patients when compared to healthy controls and/or between different time points of sampling." (PMID 33114188, 2020). "As IL-1β/IL-18 levels are reduced in Ft LVS infected Nlrp3-/- mice, the amounts of these cytokines required for protection during pulmonary tularemia may be much lower than previously thought." (PMID 27926940, 2016). "Collectively, our results show that IL-1β and IL-18 activate non-redundant protective responses against tularemia and identify an essential role for IL-1β in the rapid generation of pathogen-specific IgM by B1a B cells." (PMID 25768794, 2015). "Host cell recognition of and response to released mitochondria and other damage-associated molecular patterns engenders a sepsis-like syndrome typified by production of TNF, IL-1β, IL-6, IL-12p70, and IFN-γ during late-phase tularemia (⩾72 h), but are absent early during infection." (PMID 28955505, 2017).
viral hepatitis (8 papers, 2012 to 2024). An acute or chronic inflammation of the liver parenchyma caused by viruses. "This study examined the association between IL‐1β genotypes and depressive symptoms in 181 viral hepatitis patients, including 96 females and 85 males." (PMID 37937732, 2024). "Elevated levels of interleukin 1β (IL‐1β) have been identified in patients with chronic viral hepatitis and have been associated with depressive symptoms." (PMID 37937732, 2024). "Our findings demonstrate the association between IL‐1β polymorphisms and depressive symptoms and suggest a potential underlying mechanism for specific depressive symptoms within the chronic viral hepatitis population." (PMID 37937732, 2024). "A comparable mechanism to explain the liver involvement in viral hepatitis has been suggested by the recognized relationship between hepatic inflammation and the rise of IL-1β, TNF-α, and IL-6." (PMID 38983633, 2024). "The inflammasomes affect the pathological process of viral hepatitis through its downstream secretion of inflammatory cytokines interleukin-1β (IL-1β) and IL-18 or induction of pyroptosis resulting from cleaved gasdermin D (GSDMD)." (PMID 38817443, 2024). "This study identified three SNPs within the intronic region of the IL‐1β gene that influence the severity of depressive symptoms in individuals with chronic viral hepatitis." (PMID 37937732, 2024). "To conclude, we have comprehensively examined the relationship between depressive symptoms and IL‐1β SNPs in individuals with chronic viral hepatitis." (PMID 37937732, 2024). "Previous studies have rarely examined the influence of the IL‐1β SNPs on depressive symptoms among individuals with chronic viral hepatitis, or the specific domain affected." (PMID 37937732, 2024). "It is interesting to note, for example, that IFN-α/β therapy for viral hepatitis was ineffective in 60% of cases that could be due to the IL-1β-mediated inflammation in these patients." (PMID 36293012, 2022). "Therefore, this study aims to explore the potential influence of IL‐1β on depressive symptoms in chronic viral hepatitis patients by examining whether IL‐1β SNP genotypes affect depressive symptom phenotypes." (PMID 37937732, 2024). "Finally, since IL-1β is implicated in virus clearance, viral hepatitis does not represent good candidates for IL-1β inhibition." (PMID 30875826, 2019). "Elevated serum levels of IL-1α and IL-1β have been correlated with the impairment of hepatocytes, since they were reported to be present only in the acute and not in the recovery phase of viral hepatitis." (PMID 22384080, 2012).
visceral leishmaniasis (8 papers, 2013 to 2025). A severe form of leishmaniasis characterized by irregular bouts of fever, substantial weight loss, swelling of the spleen and liver, and anemia (which may be serious). "L. infantum, in turn, induces both pro-inflammatory IL-1β and regulatory IL-10, reflecting the complexity of visceral leishmaniasis." (PMID 41200163, 2025). "The observed anti-inflammatory activity of Ole through repression of IL-1β gene seems to be very important in the first steps of experimental visceral leishmaniasis, since IL-1β was found to be in greater necessity for CD4+ polarization to the Th2 phenotype than IL-1α." (PMID 27501956, 2016). "Indeed, IL-1α-/- mice were more resistant than IL-1β-/- mice in the experimental visceral leishmaniasis model." (PMID 27501956, 2016). "Previous reports have shown that in vivo, pro-inflammatory cytokines such as IL-1β, IL-6 and TNF-α, as well as chemokines, are induced in the initial events of L. major and L. donovani, causative agents of cutaneous and visceral leishmaniasis infection in the Old World, respectively." (PMID 23497381, 2013). "We employed ROC curve analysis to thoroughly assess the potential of IL-1β, IL-6, IL-8, IL-10, IL-12, and TNF-α as predictive biomarkers for identifying fatal cases of kala-azar." (PMID 41003560, 2025). "In the context of L. infantum-induced visceral leishmaniasis, we assessed immune mediators including TNF, IL-1β, CXCL10, IL-12p70, IL-18, IL-23, and C-C motif chemokine ligand 2 (CCL2)." (PMID 40794782, 2025). "Positive correlations were observed between the cortisol levels and the gene expression of factors related to promoting visceral leishmaniasis, such as arginase, IL-10, TGF-β, IL-1β, and IL-6." (PMID 34813597, 2021). "Concentrations of IL-1β and TNF-α are often elevated in individuals with symptomatic kala-azar." (PMID 41003560, 2025). "Although the finding of higher pre-treatment IL-1β, IL-12, and TNF-α levels in survivors suggests they serve as protective biomarkers in individuals with kala-azar, the accuracy was not sufficient for adequate diagnostic utility." (PMID 41003560, 2025). "Elevated levels of IL-1β, IL-12, and TNF-α may have a protective effect in individuals with kala-azar; however, in the present study, these cytokines did not demonstrate adequate diagnostic utility." (PMID 41003560, 2025).
vulvovaginal candidiasis (8 papers, 2014 to 2025). Infection of the vulva and vagina with a fungus of the genus CANDIDA. "Second, polymorphisms in the CIAS1 gene play a central role regulating inflammasome activity and IL-1β production, which can alter the risk of a subset of patients to developing recurrent vulvovaginal candidiasis." (PMID 25629406, 2015). "Similarly, while caspase-1-dependent secretion of the proinflammatory cytokines interleukin-1β (IL-1β) and interleukin-18 (IL-18) has potent antifungal properties, symptoms of vaginal candidiasis are largely caused by sustained influx of neutrophils due to IL-1β secretion." (PMID 25057992, 2014). "Given the crucial role of NLRP3 inflammasome-mediated IL-1β responses during vulvovaginal candidiasis (VVC), we evaluated macrophage responses to C. albicans cells grown in VSM with or without lactic acid." (PMID 39843417, 2025). "In addition, oral administration of HY7801 improves vulvovaginal candidiasis by inhibiting the survival of Candida albicans and down-regulating TNF-α, COX-2, iNOS, and IL-1β levels." (PMID 32384794, 2020).
Acute hepatitis (7 papers, 2013 to 2025). Acute hepatic injury resulting from inflammation typically accompanied by increased serum alanine transaminase activity. "The transcript level of TNF-α, TRAIL, IL-1β and IL-6 was significantly up-regulated following D-GalN Poly(I:C) induced acute hepatitis (8h) compared to D-GalN or PBS control mice." (PMID 24058536, 2013). "CA nanoparticles have also demonstrated the ability to reduce inflammation and apoptosis in acute hepatitis models by decreasing levels of TNF-α, IL-1β, and IL-18, as well as inhibiting NF-κB, NLRP3, and caspase-1, while promoting Bcl-2 levels." (PMID 40869259, 2025). "In the APAP-induced acute hepatitis model and RFP-induced chronic hepatitis model, cPBA-BE could resist GSH depletion, reduce oxidative stress, block the infiltration of neutrophils, and lower the secretion of inflammatory cytokines TNF-α and IL-1β more effectively than free BE." (PMID 34373743, 2021).
Airway obstruction (7 papers, 2011 to 2026). Obstruction of conducting airways of the lung. "Another study indicated that in COPD, IL-1β and IgE serum levels correlate with clinical aspects of disease severity and suggested that the production of both IgE and IL-1β may be related to smoking, which affects airway obstruction." (PMID 34490286, 2021). "Histological analysis of lung sections of mice treated with IL-1β showed a dramatic increase in the number and size of the foci of infiltrating inflammatory cells and evidence of perivascular edema and airway obstruction." (PMID 22241982, 2011). "Among these, IL-1β can trigger PTGS2 to induce MUC5AC mucin expression through ERK or p38 MAPK, exacerbating airway obstruction, whereas TNF-α may induce PTGS2 to produce prostaglandin E2 (PGE2) and other substances, exacerbating airway inflammation." (PMID 41557720, 2026).
alcohol abuse (7 papers, 2017 to 2025). The use of alcoholic beverages to excess, either on individual occasions ("binge drinking") or as a regular practice. "This study identifies interleukin‐1 beta (IL‐1β) in whole blood as a promising candidate biomarker of AUD risk, based on Alcohol Use Disorders Identification Test (AUDIT) scores." (PMID 40955775, 2025). "Chronic ethanol exposure in C57BL6/J mice increases pro-inflammatory cytokines in several tissues, including the heart, and clinically, IL6 and IL1β are known to be elevated with alcohol abuse." (PMID 38132102, 2023). "According with our experimental results, human studies have also shown that alcohol abuse during human pregnancy induces upregulation of cytokines (IL-1β, IL-6, and TNF-α) in both maternal blood and fetal cord levels at delivery." (PMID 28738878, 2017).
amebiasis (7 papers, 2015 to 2025). A parasitic infectious disorder caused by amoebas. "A role for Crem in regulating the NLRP3 inflammasome during amebiasis was suggested by downregulation of Il1b and Nlrp3 transcripts during acute challenge." (PMID 40576353, 2025). "Our in vivo results in an animal model of acute Eh invasion and in intact human colonic biopsies cultured with the parasite indicate the NLRP3 inflammasome plays a significant role in regulating the pro-inflammatory response in acute intestinal amebiasis by regulating IL-1β responses in the colon." (PMID 25955828, 2015). "Rather, the finding of another mechanism that relies on direct contact between macrophage and Eh, and that culminates in IL-1β release further reinforces that the intercellular junction is a hot spot for molecular events that shape the subsequent pro-inflammatory response during amebiasis." (PMID 28837696, 2017). "Our western blot results showed significant increases in the active form of NF-κB, as well as the expression of IL-1β in the ALA group, suggesting that during amoebiasis the parasite is able to stimulate the inflammatory process." (PMID 31275999, 2019).
anaphylaxis (7 papers, 1997 to 2025). An acute hypersensitivity reaction that occurs from exposure to an allergen. "In endotoxin-primed MCs, pro-IL-1β was rapidly packaged into granules after IgE-Ag stimulation and processed within granule remnants by proteases after degranulation, causing lethal anaphylaxis in mice." (PMID 38486019, 2024). "Statistically, highly significant increases in serum TSLP and IL-1β levels were also observed in individuals with multiple allergic conditions (AD + FA, AD + anaphylaxis, FA + anaphylaxis, and AD + FA + anaphylaxis)." (PMID 39860604, 2025). "The study findings indicate that the serum levels of TSLP and IL-1β were significantly elevated in patients with AD, FA, and anaphylaxis, as well as in individuals with multiple allergic conditions." (PMID 39860604, 2025). "ID showed anti-inflammatory and anti-allergic activities by suppressing skin dermatitis in DNFB-sensitized mice and compound 48/80-induced systemic anaphylaxis through the inhibition of serum IgE and IL-1β release." (PMID 26104582, 2015). "In contrast, high numbers of IL-1α-immunopositive and IL-1β mRNA expressing cells and dilated blood vessels were seen in the brain after anaphylaxis and MCAo, which indicates that these changes were initiated in response to systemic inflammatory challenge." (PMID 22114895, 2011). "Of these, we identified one biomarker that is of high importance (IL-1B), and three others (MIP-3b, TWEAK R, and Pentraxin 3) that were of critical importance during anaphylaxis." (PMID 38139075, 2023). "In the present study, roxatidine decreased mRNA levels of TNF-α, IL-6, and IL-1β in PMACI-stimulated HMC-1 and the serum of anaphylactic shock animal models." (PMID 28139747, 2017).
autoimmune uveitis (7 papers, 2010 to 2025). An autoimmune form of uveitis (disease). "Treatment of mice with IL-1β along with retinoid-binding protein injection enhanced experimental autoimmune uveitis development, whereas treatment with an anti-IL-1β antibody attenuated the inflammatory response." (PMID 34925047, 2021). "IL-1 receptor–deficient mice showed better tolerance to the experimental autoimmune uveitis animal model, further confirming the importance of IL-1β in autoimmune uveitis." (PMID 34925047, 2021). "TNF-α together with IL-1β and VEGF causes breakdown of blood-retinal barrier in a murine model of experimental autoimmune uveitis." (PMID 20467456, 2010). "In an autoimmune uveitis murine model, AhR was shown to regulate immune responses through STAT/NF-κB signaling and the subsequent production of pro-inflammatory cytokines, including TNF-α, IL-6, and IL-1β." (PMID 41300485, 2025). "Previous studies have shown that the primary function of retinal microglia in autoimmune uveitis is to initiate the disease, and without microglia, no local inflammation would develop; moreover, microglia produce cytokines such as IL-1β and IL-18 by the activation of inflammasomes." (PMID 38802924, 2024). "We found that bortezomib treatment in EAU mice could suppress not only TNF-α but also many other inflammatory mediators such as IL-1α, IL-1β, IL-12, IL-17, and MCP-1 in retinas so the autoimmune uveitis could be more effectively suppressed with bortezomib than with TNF-α antagonist etanercept." (PMID 25653480, 2015).
Bovine mastitis (7 papers, 2019 to 2025). INFLAMMATION of the UDDER in cows. "The development of bovine mastitis is closely associated with the overexpression of pro-inflammatory cytokines, particularly IL-1β, IL-6, and TNF-α, which play pivotal roles in inflammatory cascades." (PMID 40901059, 2025). "In a recent study, our group validated the inhibitory effect of glyceryl 1,3 distearate in suppressing the IL1β, IL6, IL8, and CXCL3 overexpression induced by LPS from Escherichia coli, a bacterium causing bovine mastitis." (PMID 39193343, 2024). "Pro-inflammatory cytokines, such as IL-1β, and IL-6, play a key role in inflammatory diseases including bovine mastitis, and IL-1β and IL-6 are well-studied to be involved in up-regulation of inflammatory responses." (PMID 33251265, 2020). "Pathological conditions cause altered expression levels of pro-inflammatory cytokines, such as TNF-α, which is produced early in the inflammatory response, IL-1β, which is crucial for both adaptive and innate immunity, and IL-6, which is thought to be one of the main biomarkers of bovine mastitis." (PMID 40005856, 2025). "Zophobas morio (Z. morio) hemolymph can decrease the levels of NLRP3, caspase-1 and NLRP6 and inhibit the secretion of IL-1β and IL-18, thereby attenuating E. coli- or Staphylococcus simulans (S. simulans)-induced pyroptosis; thus, it can be a new therapeutic candidate for bovine mastitis." (PMID 37845761, 2023).
cerebral palsy (7 papers, 2015 to 2024). A group of disorders affecting the development of movement and posture, often accompanied by disturbances of sensation, perception, cognition, and behavior. "Increased TNF-α and IL-1β plasma and CSF levels in term infants with asphyxia have been associated with neuroradiological alterations, poor neurological status at 12 months of age, and cerebral palsy." (PMID 29233180, 2017). "We investigated whether the risk for cerebral palsy (CP) increases when an expansion of the − 2.5 kb (CCTTT)n microsatellite in the NOS2A gene and a single nucleotide polymorphism (SNP) in -C511T of the IL- IL-1β gene promoter occur in patients after perinatal hypoxic-ischemic encephalopathy." (PMID 29931509, 2019).
conjunctivitis (7 papers, 2018 to 2025). Inflammation of the conjunctiva of the eye. "In patients with CAPS, NLRP3 mutations trigger constitutive production of IL-1β, resulting in fever, neutrophilic urticaria, conjunctivitis, arthralgia, and elevated acute-phase reactants, which can be alleviated via IL-1-blocking treatment." (PMID 35734577, 2022). "We also found that the extent of pro-inflammatory interleukin 1 beta signaling was correlated with conjunctival MG loads and the extent of clinical signs of conjunctivitis, the main pathological effect of MG in house finches." (PMID 29403495, 2018). "House finches experience an influx of local and systemic pro-inflammatory cytokine production (IL-1β, IFN-γ, TNF-α) early in infection with MG, and individual variation in conjunctivitis is significantly predicted by individual variation in local IL-1β expression." (PMID 35707121, 2022). "Moreover conjunctivitis has shown a rise in inflammatory mediators (IL-1β, TNF-α, and MMP-9) and the activation of proinflammatory mitogen-activated protein kinase (MAP-K) pathways." (PMID 34615949, 2021).